CACNB2 (calcium voltage-gated channel auxiliary subunit beta 2)
Description:
Beta subunit of voltage-dependent calcium channels which contributes to the function of the calcium channel by increasing peak calcium current (By similarity). Plays a role in shifting voltage dependencies of activation and inactivation of the channel (By similarity). May modulate G protein inhibition (By similarity). May contribute to beta-adrenergic augmentation of Ca(2+) influx in cardiomyocytes, thereby regulating increases in heart rate and contractile force. Involved in membrane targeting of the alpha-1 subunit CACNA1C.
Synonyms: CAB2; MYSB; CACNLB2; CAVB2
Tractability: Small molecule: an approved drug acts on it; a structure with a bound ligand is known; a high-quality ligand is known; it belongs to a druggable protein family. Antibody: its Gene Ontology location is reachable by antibodies, with high confidence; UniProt places it where antibodies can reach, with medium confidence. PROTAC: a small molecule that binds it is known.
Target class: Calcium channel auxiliary subunit beta family; Auxiliary transport protein
Gene: Protein-coding gene on chromosome 10 (18,140,424 to 18,543,557, forward strand). Ensembl gene ENSG00000165995.
Subcellular location: Cell membrane, sarcolemma
Pathways (Reactome):
Metabolism: Adrenaline,noradrenaline inhibits insulin secretion; Regulation of insulin secretion
Muscle contraction: Phase 0 - rapid depolarisation; Phase 2 - plateau phase
Cellular responses to stimuli: Mechanical load activates signaling by PIEZO1 and integrins in osteocytes
Developmental Biology: NCAM1 interactions
Neuronal System: Presynaptic depolarization and calcium channel opening
Sensory Perception: Sensory processing of sound by inner hair cells of the cochlea
Gene Ontology:
Molecular function: high voltage-gated calcium channel activity; protein binding; voltage-gated calcium channel activity; voltage-gated calcium channel activity involved in AV node cell action potential; voltage-gated calcium channel activity involved in cardiac muscle cell action potential; actin filament binding; calcium channel activity; voltage-gated calcium channel activity involved in regulation of presynaptic cytosolic calcium levels
Biological process: calcium ion import; membrane depolarization during atrial cardiac muscle cell action potential; membrane depolarization during AV node cell action potential; positive regulation of calcium ion transport; regulation of heart rate by cardiac conduction; calcium ion transmembrane transport; calcium ion transport; chemical synaptic transmission; neuromuscular junction development; positive regulation of calcium ion transmembrane transport via high voltage-gated calcium channel; positive regulation of muscle contraction; protein localization to plasma membrane; regulation of presynaptic cytosolic calcium ion concentration
Cellular component: L-type voltage-gated calcium channel complex; voltage-gated calcium channel complex; plasma membrane; T-tubule; photoreceptor ribbon synapse; presynapse; sarcolemma
Genetic constraint (gnomAD): Loss-of-function variants: 31 observed, 54.32 expected, observed/expected ratio (o/e) 0.57, 90% interval 0.43 to 0.77. The upper end of that interval is the gene's LOEUF score, 0.77, which puts it in group 3 of 6, group 1 being the genes least tolerant of losing a copy. Missense variants: 836 observed, 781.42 expected, observed/expected ratio (o/e) 1.07, 90% interval 1.01 to 1.13. Synonymous variants: 314 observed, 287.56 expected, observed/expected ratio (o/e) 1.09, 90% interval 1 to 1.2.
Gene-disease validity (ClinGen):
ClinGen rates the evidence that CACNB2 causes each of these diseases.
cardiogenetic disease (autosomal dominant): Disputed. A heterogeneous group of genetic conditions, with Mendelian (autosomal dominant, recessive, or X-linked) or chromosomal etiology that are characterized by abnormalities in the cardiovascular system.
Homologues: Orthologues: chimpanzee CACNB2 (99% identical), macaque CACNB2 (99% identical), rat Cacnb2 (93% identical), pig CACNB2 (92% identical), rabbit CACNB2 (92% identical), dog CACNB2 (91% identical), guinea pig CACNB2 (91% identical), mouse Cacnb2 (86% identical), tropical clawed frog cacnb2 (84% identical), zebrafish cacnb2a (61% identical), Drosophila melanogaster Ca-beta (49% identical), Caenorhabditis elegans ccb-1 (45% identical), and 1 more. Paralogues in human: CACNB1 (61% identical), CACNB4 (53% identical), CACNB3 (46% identical).
Diseases named in the same sentence as CACNB2 in open-access papers:
CACNB2 is named in the same sentence as 62 diseases in open-access papers, as found by Europe PMC text mining. Sharing a sentence is not in itself a finding about the gene and the disease. The quoted sentences say what the papers report.
schizophrenia (24 papers, 2013 to 2024). A major psychotic disorder characterized by abnormalities in the perception or expression of reality. "Genome-wideassociation studies on ancestrally diverse populations have repeatedly identified calcium voltage-gated channel auxiliary subunit beta 2(CACNB2) as the risk loci associated with MDs such as schizophrenia andbipolar disorder." (PMID 39355592, 2024). "For two genes, i.e., CTCF and CACNB2, evidence for association with schizophrenia was available (at the gene level) in both the discovery study and the published data from the Psychiatric Genomics Consortium schizophrenia study." (PMID 35328011, 2022). "CACNB2 polymorphism is reported to confer susceptibility to schizophrenia and other neurological disorders and possibly regulates neuronal differentiation." (PMID 31487305, 2019). "Variation at the CACNB2 locus has been found to increase risk for schizophrenia and for the five psychiatric disorders, schizophrenia, BD, MDD, ASD and attention deficit hyperactivity disorder, included in a recent cross-disorder GWAS." (PMID 26798408, 2016). "For two genes, i.e. CTCF and CACNB2, evidence for association with schizophrenia was available (at the gene-level) in both the discovery study and published data from the Psychiatric Genomics Consortium schizophrenia study." (PMID 24901509, 2014). "Notably, CACNB2, which encodes a subunit of a voltage-dependent calcium channel protein that is critical for mediating intracellular Ca2+ influx, has been established as a risk gene for psychiatric disorders such as schizophrenia and bipolar disorder." (PMID 38291185, 2024). "Moreover, in a recent GWAS study CACNB2 was identified among four significant risk loci underlying genetic effects shared between five major psychiatric disorders that included schizophrenia, autism spectrum disorder, attention deficit-hyperactivity disorder, bipolar and major depressive disorders." (PMID 31181069, 2019). "Three loci have been reported to have combined association with both schizophrenia and BD (CACNA1C, CACNB2, and ITIH3-ITIH4), and one locus, which was previously found to be associated with BD (NCAN)." (PMID 34502224, 2021). "A recent trans-ancestry meta-analyses of Chinese and PGC2 samples (a total of 43,175 cases and 65,166 controls) further supports the association between CACNB2, CACNA1C, CACNA1I genes and schizophrenia." (PMID 29308060, 2018). "Combined with the genetic results implicating L-type calcium channel genes CACNA1C and CACNB2 in schizophrenia, depression, bipolar disorder, autism, and ADHD, this model further implicates Ca2+ channels in neuropsychiatric illness." (PMID 25762938, 2015). "It has been shown that genes related to Ca2+ signaling, such as the CACNA1C, CACNB2, and CACNA1I genes that encode VGCC subunits, are associated with schizophrenia and other psychiatric disorders." (PMID 26136667, 2015). "In schizophrenia, both CACNA1C and ANK3 were identified, and in bipolar disorder TRANK1 and CACNB2 were also significantly associated." (PMID 23637625, 2013). "In particular, CTCF, CACNB2, and ARL5B, i.e. genes involved in chromatin modulation, calcium channel signaling and membrane transport, respectively, were highlighted as candidate genes for schizophrenia risk." (PMID 24901509, 2014). "Several of the SNVs assigned to CTCF and CACNB2 have potential functional consequences, and a gene in close proximity to CACNB2, i.e., ARL5B, was identified as a potential gene of interest in schizophrenia and depressive disorder comorbidity." (PMID 35328011, 2022). "Several of these genomic markers are shared between BD and schizophrenia such as CACNA1C, CACNB2, NCAN, TRANK1, ITIH3-ITIH4, and ANK3." (PMID 34502224, 2021). "Interestingly, none of the reproducible GWAS-associated loci in schizophrenia CACNA1C, CACNA1H, and CACNB2 (Schizophrenia Working Group of the Psychiatric Genomics, 2014) was detected in our dataset." (PMID 28713243, 2017).
bipolar disorder (11 papers, 2013 to 2022). A disorder of the brain that causes unusual shifts in mood, energy, activity levels and the ability to carry out day-to-day tasks. "CACNB2 is a calcium channel protein linked to diabetic retinopathy, bipolar disorder, hypertension and autism spectrum disorders." (PMID 33245713, 2020). "A single-nucleotide polymorphism at the CACNB2 gene (rs11013860) has been reported in genome-wide association studies to be associated with bipolar disorder (BD)." (PMID 30744588, 2019). "Thus, the current study investigated the mechanisms of how the CACNB2 gene influences hippocampal-cortical limbic circuits in patients with bipolar disorder (BD)." (PMID 30744588, 2019). "Recently, CACNB2 was among four loci with genome-wide significance in a cross-disorder analysis of GWAS data for autism spectrum disorder, attention deficit-hyperactivity disorder, bipolar disorder, major depressive disorder, and SCZ." (PMID 24901509, 2014).
Hypertension (10 papers, 2009 to 2025). The presence of chronic increased pressure in the systemic arterial system. "The CACNB2 gene has been reported in a previous genome-wide association study of blood pressure and hypertension." (PMID 36845374, 2023). "Association analyses in China, Lithuanian and Europe have reported the association between CACNB2 polymorphisms (rs4373814 in Chinese Han, rs12258967 in Lithuanian and rs18748804 in Europe) and hypertension." (PMID 32111194, 2020). "One of these studies also reported finding significant hits in the CACNB2 gene for hypertension and DBP, a gene with a high-scoring variant for hypertension in the present study and in the PMS1 gene for hypertension and SBP, which scored highly for SBP in this study." (PMID 19609347, 2009). "Studies have shown that CACNB2 was associated with DBP, systolic pressure, mean arterial pressure, and hypertension." (PMID 39840108, 2024). "For evaluation of genotype effect on the risk of hypertension, four SNPs were chosen: two SNPs (AGT and ACE) related to renin-angiotensin-aldosterone system and other two SNPs (ADM and CACNB2) newly identified in genome-wide association studies." (PMID 25313554, 2014). "Among new identified loci for hypertension there are genes encoding ADM and CACNB2." (PMID 25313554, 2014). "In this study, the SNPs identified in the CACNA1S, CACNB2 and CACNA1S genes suggest a different molecular pathogenesis of hypertension in Dai people." (PMID 32111194, 2020). "The CACNB2 and CACNA1D genes have shown network with coronary diseases, hypertension, diabetes, BPD and depression." (PMID 28117839, 2017).
Brugada syndrome (9 papers, 2013 to 2025). A genetically heterogeneous condition characterized by complete or incomplete right bundle branch block accompanied by ST elevation in leads V1-V3. "WES, focusing on genes associated with Brugada syndrome, revealed he was heterozygous for g.15206G>T splice acceptor variant in the CACNB2 gene." (PMID 41282474, 2025). "A variant in CACNB2 causes phenotypic overlap between Brugada syndrome and short QT syndrome as well." (PMID 37270590, 2023). "Methods and results: This study recruited cells from a patient with Brugada syndrome (BrS) and recurrent ventricular fibrillation carrying a missense variant in CACNB2 as well as from three healthy independent persons." (PMID 35955449, 2022). "Mutations in CACNB2 have been implicated in a form of Brugada syndrome, a genetic disease characterized by electrocardiogram abnormalities." (PMID 23704328, 2013). "A non-synonymous variant in CACNB2 has been shown to be responsible for Brugada's syndrome, a heritable sudden cardiac death syndrome." (PMID 24400021, 2013). "Variants in CACNB2 are generally connected to Brugada syndrome, SUD, or arrhythmias." (PMID 36346469, 2023). "There were no variants in SCN5A, which is classically associated with Brugada syndrome; however, the CACNB2 gene defects also result in Brugada syndrome." (PMID 41282474, 2025). "In contrast, rare variants located in genes encoding calcium (CACNA1C, CACNA2D1, and CACNB2) and the SCN5A gene, have been associated with Brugada syndrome (BrS) concomitant with shortened QT intervals, but without a conclusive diagnosis of SQTS." (PMID 30420954, 2018).
depression (9 papers, 2014 to 2024). "It was thus indicated that there may be a population-specific effect of CACNB2 polymorphisms on the risk of depression." (PMID 38800057, 2024). "Findings from another recent study suggest that CACNB2, one of the drug targets of CCBs, was associated with a lower risk of depression in East Asian populations but not in the European populations." (PMID 38800057, 2024). "Common variants in MTR, PPARA, ABCC3, CALML5, CACNB2 and PCDHB10 genes were associated with deficits in neurocognitive tests performance, whereas a variant in SLCO1B1 and EPHA5 genes was associated with anxiety and depression." (PMID 31181069, 2019). "Functionally predicted germline common variants in MTR, PPARA, SLCO1B1, ABCC3, CALML5, CACNB2 and PCDHB10 genes were found to be significantly associated with deficits in neurocognitive tests performance, whereas a variant in EPHA5 gene was significantly associated with both anxiety and depression." (PMID 31181069, 2019).
epilepsy (7 papers, 2017 to 2025). A brain disorder characterized by episodes of abnormally increased neuronal discharge resulting in transient episodes of sensory or motor neurological dysfunction, or psychic dysfunction. "Other common genes including MTHFR, GSTM1, CYP17A1, and CACNB2 are implicated in neurological disorders such as epilepsy." (PMID 34899152, 2021). "Exome sequencing has identified various mutations of CACNA1D in ASD, epilepsy developmental delay endocrine issues, CACNA2D1 in epilepsy and intellectual disability and CACNB2 mutations in ASD." (PMID 33338084, 2020). "Bioinformatics analysis revealed that the effects of AS3MT on epilepsy likely involved multiple targets including MTHFR, GSTM1, CYP17A1, NT5C2, YBX3, CNNM2, CACNB2, and TRIM26." (PMID 34899152, 2021). "The effects of AS3MT on epilepsy might involve multiple targets including CNNM2, CACNB2, TRIM26, MTHFR, GSTM1, CYP17A1, NT5C2, and YBX3." (PMID 34899152, 2021).
Arrhythmia (6 papers, 2015 to 2024). Any cardiac rhythm other than the normal sinus rhythm. "The phenotypic features of BrS patients in presence of CACNB2 variant were successfully recapitulated in the hiPSC-CMs, including reduced peak ICa-L, reduced protein level of CACNB2 and increased arrhythmia events at baseline." (PMID 35955449, 2022). "Male, but not female, CIH rats have altered expression of Cav3, Cacna1c, Cacnb2, Kcne5, Kcnd2, and Hcn2 which may preferentially predispose postnatal males to develop arrhythmia." (PMID 38981849, 2024). "Mutations in LTCC genes, including CACNA1C, CACNA1D, CACNB2 and CACNA2D, will induce the dysfunctions of calcium channels, which result in the abnormal excitations of cardiomyocytes, and finally lead to cardiac arrhythmias." (PMID 30027834, 2018). "In another case, where arrhythmia, early repolarisation syndrome (ERS), or Brugada was suspected, a VUS in CACNB2, NM_201590.3:c.1717C > T, was detected." (PMID 36346469, 2023).
mental disorder (4 papers, 2019 to 2024). A disease that has its basis in the disruption of mental process. "Mutations in Cavβ2, encoded by the CACNB2 gene, are associated with mental disorders and cardiovascular diseases." (PMID 38348884, 2024). "In the last few years, both GWAS and Integrated Pathway-Based Studies have identified associations between SNPs in CACNB2 and serious mental disorders, including BD." (PMID 30744588, 2019). "For example, CACNA1C is harmful in Europeans but not in East Asians, while CACNB2 is associated with a higher risk of mental disorders in East Asians." (PMID 38166843, 2024). "Given important role that CACNB2 can play, it is not surprising that it was studied as a possible pharmacological target in treatment of mental disorders." (PMID 31181069, 2019).
short QT syndrome (4 papers, 2021 to 2023). A genetic disease of the electrical system of the heart that consists of a constellation of signs and symptoms, consisting of a short QT interval on an EKG (< 300 ms) that does not significantly change with heart rate, tall and peaked T waves, and a structurally normal heart. "In another study using hiPSC-CMs, calcium voltage-gated channel auxiliary subunit beta 2 (CACNB2) variant c.1439C>T/p.S480L was found to be associated with short QT syndrome 5 (SQTS5) phenotype overlapping with BrS." (PMID 37830612, 2023). "Recently published data reported that variants in the alpha-subunit (CACN1C) and beta-subunit (CACNB2) of the L-type calcium channel are linked to BrS and/or short QT syndrome." (PMID 35955449, 2022).
diabetes (3 papers, 2013 to 2021). "The five increased calcium genes (Myl6b, Casq2, Itga7, Cacnb2 and Sln) have not had changed expression in previous diabetes studies." (PMID 24199937, 2013).
diabetic retinopathy (3 papers, 2013 to 2023). "There was only one article showing a relationship of the CACNB2 gene (OR < 1) with diabetic retinopathy." (PMID 37324619, 2023).
autism (2 papers, 2014 to 2022). Persistent deficits in social interaction and communication and interaction as well as a markedly restricted repertoire of activity and interest as well as repetitive patterns of behavior. "In conclusion, the results of our first-time biophysical characterization of these three rare CACNB2 missense mutations identified in ASD patients support the hypothesis that calcium channel dysfunction may contribute to autism." (PMID 24752249, 2014).
coronary artery disease (2 papers, 2013 to 2017). "CACNB2 SNPs were genotyped in the INternational VErapamil SR-Trandolapril STudy-GENEtic substudy (INVEST-GENES), a outcomes study including 5598 hypertensive patients with coronary artery disease who were randomized to either a β-blocker or a calcium channel blocker." (PMID 24400021, 2013).
dilated cardiomyopathy (2 papers, 2021 to 2025). Cardiomyopathy which is characterized by dilation and contractile dysfunction of the left and right ventricles. "We found that CACNB2 was significantly downregulated in atrial tissues from patients with persistent AFib, which confirms Ca2+ handling impairment during electrical atrial remodeling as previously reported in chronic Afib and dilated cardiomyopathy." (PMID 34737791, 2021).
heart failure (2 papers, 2020 to 2022). Inability of the heart to pump blood at an adequate rate to meet tissue metabolic requirements. "Finally, CACNB2, KCNAB2, and TIMM22 encode subunits that participate in dysfunctional voltage-gated channels that may be associated with arrhythmia events rather than aggravated heart failure." (PMID 32802835, 2020).
Achalasia (1 paper, 2016). A disorder of esophageal motility characterized by the inability of the lower esophageal sphincter to relax during swallowing and by inadequate or lacking peristalsis in the lower half of the body of the esophagus. "We observed a number of sequences involving the calcium signaling pathway (ie, CACNA1C, CACNB2, KCNMA1, CHRM2, CAV1, and NCS1) that were differentially expressed and were able to characterize these genes into possible functions related to achalasia pathogenesis." (PMID 27511445, 2016).